INS (insulin)
Diseases named in the same sentence as INS in open-access papers (continued):
Sharing a sentence is not in itself a finding about the gene and the disease.
Hepatic steatosis (continued). "Apob mutant mice are quite phenotypically similar to MTTP-deficient mice, developing hepatic steatosis without a disruption in glucose or insulin tolerance." (PMID 32907986, 2020). "Additionally, intervention with this Clostridium increased SCFA, improved intestinal permeability, insulin resistance and hepatic steatosis." (PMID 33292434, 2020). "Serum lipids, liver steatosis, oxidative stress and insulin sensitivity were determined." (PMID 32074961, 2020). "Furthermore, insulin increases fat biosynthesis in the liver, thus influencing the pathogenesis of fatty liver." (PMID 32471118, 2020). "In the responder group, amlexanox improved insulin sensitivity and hepatic steatosis." (PMID 33193441, 2020). "N. sativa supplementation (2 g/day for 12 weeks) in patients who have cardiovascular disorders risk factors and also in patients with NAFLD 2 significantly decreased glucose and insulin serum levels and also decreased hepatic steatosis percentage compared to the placebo." (PMID 33062002, 2020). "Mouse models show reduced hepatic steatosis when insulin sensitivity is improved." (PMID 32286259, 2020). "As expected, our results indicated that liraglutide could dramatically alleviate the insulin aggravated fatty liver in vitro." (PMID 33746742, 2020). "Whether the improvement of hepatic steatosis in these mouse models is a direct outcome of transcriptional regulation by Xbp1 or a secondary consequence of resolved metabolic stress and improved insulin sensitivity remains unclear." (PMID 32660130, 2020). "The two doses of crude aqueous noni fruit extract (AE) used in the study, AE 250 and AE 500, under the influence of the HFF diet were not able to diminish body weight or the visceral adiposity gain, total cholesterol, triglycerides, insulin levels, systemic insulin resistance, or hepatic steatosis." (PMID 33182564, 2020). "The efficacy of these anti-diabetic drugs against hepatic steatosis might be limited due to their mode of action, which mostly focuses on enhancing glucose clearance and/or insulin production but insulin resistance." (PMID 32286259, 2020). "This makes it difficult to determine whether the reduced hepatic steatosis is due to greater insulin sensitivity or lower insulin levels." (PMID 32286259, 2020). "Therefore, linagliptin seemed to ameliorate OSI-906-induced hepatic steatosis independently of the fatty acid flux to the liver, consistent with the regulation of fatty acid metabolism via insulin." (PMID 33105604, 2020). "As the combination treatment tends to be the most promising solution suggested by the latest AACE/ACE clinical practice guidelines, we proposed that the combined liraglutide and insulin treatment might alleviate insulin aggravated hepatic steatosis." (PMID 33746742, 2020). "Studies have shown that PPARγ participates or regulates the fat deposition in liver by affecting the biological processes of hepatic lipid metabolism, insulin resistance, gluconeogenesis, oxidative stress, endoplasmic reticulum stress and inflammation, which all contribute to fatty liver." (PMID 32272794, 2020). "In some cell culture studies and animal experiments, very-long-chain ceramides also play a protective role in liver homeostasis, hepatic steatosis, myelin maintenance, apoptosis, and insulin resistance by influencing cell membrane properties and cell signaling." (PMID 32899794, 2020). "In sum, these data clearly indicate that the lack of adipocyte Gi signaling caused liver steatosis and hepatic insulin resistance." (PMID 32532984, 2020).
Hepatic steatosis (continued). "One study also suggested that the favorable effects of a bitter melon water extract on increasing insulin sensitivity and attenuating hepatic steatosis may be mediated by enhanced AMP-activated protein kinase (AMPK) and sirtuin (SIRT1) signaling." (PMID 32354072, 2020). "In conclusion, the study supports our hypothesis that reduced endogenous insulin in E4orf1-Tg mice contributes to reduced hepatic steatosis." (PMID 32286259, 2020). "In mice under a high-fat diet, 12-week intraperitoneal administration of urolithin A (20 μg/day) significantly improved systemic insulin sensitivity, attenuated liver steatosis, and reduced adipocyte hypertrophy and macrophage infiltration into the adipose tissue." (PMID 33287432, 2020). "Moreover, we recently found that inhibition of extracellular CTSD activity reduced plasma insulin levels and hepatic lipids in rats with hepatic steatosis." (PMID 33101209, 2020). "We have previously shown that 17α-E2 can reduce hepatic steatosis, hepatic insulin resistance, and hepatocyte DNA damage through unknown mechanisms." (PMID 33289482, 2020). "In addition, a recent study also confirmed that paeoniflorin significantly reduced serum insulin and glucagon levels, enhanced insulin sensitivity, restored serum lipid profiles, and attenuated hepatic steatosis." (PMID 32410996, 2020). "Moreover, low-dose clenbuterol stimulated basal in vivo glucose uptake in skeletal muscle and improved whole-body insulin sensitivity as well as reduced hepatic steatosis under chronic stimulation in DIO mice." (PMID 32472192, 2020). "Therefore, peanuts rich in oleic acid can suppress the primary mechanisms of fatty liver disease manifested as decreased fat accumulation in the liver, decreased plasma fatty acid flow followed by improved insulin sensitivity." (PMID 33033472, 2020). "Based on HOMA2%-S, individuals with fatty liver were more insulin resistant than controls." (PMID 31097978, 2019). "The inhibition of de novo ceramide synthesis has been demonstrated to decrease hepatic steatosis and improve insulin resistance in animal models, suggesting that either temperature may be efficacious in strategies targeting lipid modulation." (PMID 31652927, 2019). "Moreover, animal studies showed that inhibiting secretion of VLDL from the liver by genetic modification resulted in liver steatosis with conserved insulin sensitivity." (PMID 31447675, 2019). "Thus, genetic loss of HSL in mouse ATs can release ChREBP-α, leading to enhanced mice insulin sensitivity, albeit the mice concurrently develop hepatic steatosis." (PMID 31623194, 2019). "Therefore, maladaptive processes implicated in hepatic steatosis and liver inflammation are associated with the central effects of TNF on insulin dysregulation." (PMID 31892368, 2019). "Therefore, PNPLA3 rs738409 C > G variant carriers, with a shift of DAG distribution and composition, would present seemingly paradoxical severe liver steatosis and conserved insulin sensitivity." (PMID 31447675, 2019). "Nevertheless, in a randomized trial (n = 67), lower insulin levels, inflammatory markers and reduced hepatic steatosis (assessed by magnetic resonance (MRI) or 1H NMR) were evidenced after a 10-week isocaloric diet supplemented with omega-6 PUFAs vs. saturated fat supplementation." (PMID 30901929, 2019). "In mice fed a Western diet, RDX8940 improved liver steatosis and insulin sensitivity." (PMID 30605011, 2019). "More importantly, we showed that the increase in serum ghrelin hormone levels after chronic ethanol consumption is responsible for impaired insulin secretion from the pancreas and the consequences delineated above, which leads to the development of hepatic steatosis." (PMID 31546643, 2019).
Hepatic steatosis (continued). "Corroborating with that the expression of miR-94 was decreased in the liver of HFD-fed mice beside an increase of Apoa5 that could, along with other factors, be responsible for the impairment of insulin sensitivity and liver steatosis observed in our study." (PMID 31885789, 2019). "CT-1 has been shown to promote insulin-stimulated glucose uptake in myotubes and cultured adipocytes, to modulate the production of other adipokines and to exert protective effects against liver apoptosis, hepatocyte injury, hepatic steatosis and renal damage." (PMID 31013924, 2019). "RDX8940 pharmacokinetics and effects on GLP secretion, insulin sensitivity, and liver steatosis were assessed in C57BL/6 mice fed normal or Western diet chow and given single or repeated doses of RDX8940 or vehicle, with or without dipeptidyl peptidase-4 (DPP4) inhibitors." (PMID 30605011, 2019). "However, worsening absolute values of glucose, insulin, and HbA1c were found in the group with hepatic steatosis at baseline, despite the WC reduction." (PMID 31275240, 2019). "Additionally, blocking peripheral CB1R improves insulin sensitivity and glucose metabolism and also reduces hepatic steatosis and body weight in obese mice." (PMID 31035653, 2019). "Indeed, multiple phosphorylation sites, some of which are regulated by insulin-signaling, have been identified in NCOR and other core subunits in the context of mouse liver steatosis and insulin signaling." (PMID 31293521, 2019). "Given that Mboat7 knockdown promoted striking hepatic steatosis, and the fact that adipose tissue expression of Mboat7 is negatively correlated with insulin sensitivity across strains of the HMDP we examined glucose homeostasis in Mboat7 ASO-treated mice fed a high fat diet." (PMID 31621579, 2019). "Their effect on a more efficient insulin signaling via the Akt pathway might be a positive influence against liver steatosis." (PMID 30901929, 2019). "Our findings suggest that liver steatosis induced by disrupted insulin signaling may be an early predictor of T1D development and this could result in a loss of immune tolerance in the liver." (PMID 31601915, 2019). "This improvement in body weight gain may be associated with the improvement of lipid profile, liver function, insulin level, antioxidant system and reduction of the severity of fatty liver disease, which collectively lead to better metabolism and growth." (PMID 31570745, 2019). "Finally, and of translational relevance, we found that hepatic TMEM127 expression correlates with fatty liver disease and insulin-resistant states both in mice and in humans." (PMID 31624249, 2019). "Major impacts on insulin signaling are observed under conditions of hepatic steatosis." (PMID 29717275, 2018). "All changes were justified by the effects ofyerba mate on insulin sensitivity.Another study showed that treatment of obese mice with yerba mate for seven weeksalso improved liver steatosis and increased peripheral insulin sensitivity, inaddition to promoting a reduction of adipocyte proliferation." (PMID 29791596, 2018). "We thus hypothesize that the combination of ketogenic diet and exercise could improve insulin sensitivity, while minimizing adverse effect of hepatic steatosis." (PMID 29743883, 2018). "The activation of hepatic nuclear receptors by BA stimulates lipid oxidation and may protect obese patients from hepatic steatosis and hepatic insulin resistance." (PMID 30477108, 2018). "When fed a high-fat diet, mice overexpressing Nrg4 specifically in the liver and adipose tissues gained significantly less weight than control mice and exhibited improvements in glucose tolerance, lipid metabolism, and insulin sensitivity, and decreased hepatic steatosis." (PMID 29721105, 2018).
Hepatic steatosis (continued). "We demonstrate that hepatic spheroids from different donors of various age and original phenotype are capable of mimicking the pathological condition of hepatic steatosis, excess di- and triglyceride accumulation in the liver, following treatment with various nutrients and insulin." (PMID 30250238, 2018). "This led to speculation that the decreased IRS-2 in hepatic steatosis is the main contributor to impairment of the insulin signaling that governs the suppression of hepatic glucose production." (PMID 29717275, 2018). "Hepatic steatosis was induced over the course of three weeks in culture by supplementing the culture medium with pathophysiological concentrations of free fatty acids, carbohydrates and insulin." (PMID 30250238, 2018). "Moreover, CD36 plays an active role in fatty acid uptake and has significant effects on hepatic steatosis and insulin sensitivity." (PMID 30037134, 2018). "In conclusion, in acromegaly HSI is mainly related with IR and the reduction of GH and IGF-1 levels, and above all the improvement in insulin sensitivity leads to an improvement of this surrogate index of hepatic steatosis, which should always be evaluated in the follow-up of acromegalic patients." (PMID 30662461, 2018). "Overall, MCFA could constitute an effective nutritional tool to manage liver steatosis and hepatic insulin resistance." (PMID 30208604, 2018). "Berberine (BBR) has been reported to improve insulin sensitivity in mice with hepatic steatosis." (PMID 29882814, 2018). "Many studies showed that rosiglitazone and pioglitazone significantly improved hepatic steatosis, and this effect of these drugs is largely explained by the secondary effect of improving the insulin sensitivity of adipose tissue, where PPARγ level is mainly high." (PMID 30008738, 2018). "Additionally, studies have shown that the PPARα ligand can effectively lower blood lipid levels, increase insulin sensitivity, and reduce hepatic steatosis." (PMID 30428868, 2018). "A study by Mottillo and colleagues utilized an inducible model for deletion of the two AMPK β subunits in adipocytes (iβ1β2AKO), whereby deletion of AMPK exacerbated the insulin resistant phenotype in terms of hepatic steatosis and glucose tolerance in response to an HFD." (PMID 30304866, 2018). "After 6-week intervention, we found that diabetic mice in ketogenic diet intervention significantly improved insulin sensitivity while exhibiting hepatic steatosis, which could be largely relieved by aerobic exercise." (PMID 29743883, 2018). "Moreover, moderate alcohol intakes enhance insulin sensitivity, and are likely to prevent the onset of metabolic diseases, including fatty liver disease." (PMID 29664906, 2018). "Rapamycin—an autophagy enhancer—reduces hepatic steatosis and raises insulin sensitivity." (PMID 28452943, 2017). "The protective effects of Timp4 gene deletion on hepatic steatosis could also be due to the decreased insulin levels in HFD-fed mice as insulin is a potent activator of hepatic lipogenesis." (PMID 28740132, 2017). "Thus, the shift towards lipogenesis over FA oxidation contribute to hepatic steatosis and, hence, in a vicious circle, to insulin resistance." (PMID 29057834, 2017). "Subsequently, alleviation of hepatic steatosis may contribute to lessen hepatic inflammation, dampen hepatic ER stress and improve insulin sensitivity in an optimal cycle." (PMID 28831172, 2017). "In conclusion, attenuation of the hepatic steatosis by pioglitazone may be conferred by refining insulin sensitivity, intensifying cytosolic lipolysis, β-oxidation and lipophagy-mediated lysosomal lipolysis in a manner of PPARα/γ dependently." (PMID 28831172, 2017). "After observing significantly higher hepatic steatosis (1st hit) and the end point hepatic fibrosis in WT-FF, we therefore evaluated potential 2nd hit factors such as oxidative stress, endotoxemia, hepatic inflammation, ER stress, and insulin resistance." (PMID 28051126, 2017).
Hepatic steatosis (continued). "Using Liver-ChREBP KO mice, we investigated whether hepatic ChREBP deletion influences insulin sensitivity, glucose homeostasis and the development of hepatic steatosis utilizing various dietary stressors." (PMID 29107286, 2017). "However, targeted deletion of CTRP9 increases food intake, decreases insulin sensitivity, and promotes hepatic steatosis in mice." (PMID 28348559, 2017). "The improvement in hepatic steatosis may result from enhanced intrahepatic insulin sensitivity after FMT." (PMID 28484247, 2017). "Therefore, exposing obese mice to very low temperatures markedly improved insulin sensitivity and liver steatosis." (PMID 28239649, 2017). "Improvement of insulin sensitivity and hepatic steatosis in obese mice." (PMID 28239649, 2017). "Overexpression of SIRT1 in mice attenuates hepatic steatosis and improves insulin sensitivity." (PMID 28904866, 2017). "However, hepatic steatosis was more severe and insulin sensitivity was reduced in Atp4aSl/Sl mice on a HFD compared to WT mice on a HFD." (PMID 29038503, 2017). "For example, reduced plasma insulin and plasma triglyceride levels as well as an improvement of hepatic steatosis were observed in HFD-fed mice and rats in which liver-specific knockdown of Indy was accomplished using a low-dose of a chimeric anti-sense oligonucleotide." (PMID 28596784, 2017). "Furthermore, Satoch and coworkers demonstrated that hepatic steatosis is induced by an increase in incorporation of fatty acids into the liver via increased Ppar-γ expression in the liver of insulin-resistant mice." (PMID 29113135, 2017). "Furthermore, we found that BMI (kg/m2) is more impactful for child liver steatosis (r = 0.696, p < 0.001) than insulin resistance (r = 0.510, p < 0.001)." (PMID 28759573, 2017). "Unfortunately, we were not able to find the underlying mechanism that connects hepatic steatosis with defective insulin signaling beyond the IRS1/PI3K reduction." (PMID 29028831, 2017). "Hepatic steatosis occurs when impaired insulin signaling results in compensatory hyperinsulinemia." (PMID 28933748, 2017). "Since MnP reduced liver steatosis and maintained insulin sensitivity, we sought to determine whether MnP, in turn, would reduce the effects of these phenomena in our disease model." (PMID 29104232, 2017). "A decrease in insulin signaling reportedly results in the inhibition of gluconeogenesis suppression and hepatic steatosis in the liver and a reduction of glucose uptake in muscle, suggesting that insulin signaling is important in glucose homeostasis in the body." (PMID 28886131, 2017). "Liver PPARγ regulates fatty acid uptake, and trafficking, as well as TG biosynthesis, which contributes to hepatic steatosis and demonstrates positive associations with serum insulin levels and HOMA-IR and negative correlations with total adiponectin." (PMID 28578672, 2017). "Overweight and obese children have been reported to account for 81% of all cases of fatty liver disease, and insulin resistance would result in increased lipolysis from adipose tissue and increased lipid influx into the liver, promoting hepatic fat accumulation." (PMID 28759573, 2017). "Collectively, these data provide strong evidence that hepatic Fas signaling may be a pharmacological target to treat fatty liver disease and to improve hepatic insulin sensitivity." (PMID 28883393, 2017). "In this study we found that mice lacking triacylglycerol hydrolase (TGH, also known as carboxylesterase 3 or carboxylesterase 1d) are protected from high-fat diet (HFD) - induced hepatic steatosis via decreased lipogenesis, increased fatty acid oxidation and improved hepatic insulin sensitivity." (PMID 27181051, 2016). "Using a randomised controlled trial design, this study compares the effectiveness of the Mediterranean diet to a standard low fat diet in terms of differences in insulin sensitivity, hepatic steatosis and metabolic outcomes in participants with non-alcoholic fatty liver disease." (PMID 26831892, 2016).